CRP (C-reactive protein)
Diseases named in the same sentence as CRP in open-access papers (continued):
Sharing a sentence is not in itself a finding about the gene and the disease.
Sepsis (continued). "Specific biomarkers such as C-Reactive Protein (CRP), Procalcitonin (PCT), Interleukin-6 (IL-6), D-dimers, and Fibronectin were included alongside routinely used markers in several studies, highlighting the role of these inflammatory and coagulation markers in sepsis prognosis." (PMID 39767798, 2024). "Given that amphiregulin was dynamically elevated in some cases of sepsis without a CRP rise and vice versa, we hypothesized that development of a test for sepsis that combined both parameters would increase test accuracy to ‘rule-out’ sepsis." (PMID 38195661, 2024). "Compared with PCT and CRP, the PSP biomarker, with its unique applications and properties that may potentially benefit patients, doctors and hospitals, performed well and proved reliable in diagnosing sepsis in adult patients." (PMID 39416748, 2024). "Notably, FC levels did not decrease in SIRS/sepsis compared to controls but were positively correlated with CRP." (PMID 39311203, 2024). "While PCT exhibits superior diagnostic performance compared to CRP, with a higher AUC of 0.82 versus 0.78, it is important to note that elevated PCT levels indicate the presence of bacterial infections rather than definitively confirming sepsis." (PMID 39469363, 2024). "CRP, PCT and PSP offer benefits that are unique in certain aspects and may be useful not only to diagnose but to improve patient care among individuals with or suspected sepsis." (PMID 39416748, 2024). "In addition to dysregulated amounts of blood components (WBCs, CRP, PTC, and platelets), sepsis blood may also contain microorganisms." (PMID 38920613, 2024). "Therefore, monitoring CRP and PCT levels in sepsis patients should be emphasized." (PMID 39039452, 2024). "Our results showed even though CRP has a high value to identify NEC from control, but with limited value to distinguish NEC and sepsis, which could be related with that NEC is easy to induce sepsis." (PMID 36806964, 2023). "Patients suspected of having sepsis underwent a Sequential Organ Failure Assessment (SOFA) evaluation and had blood drawn for blood cultures, complete peripheral blood counts (CBC), and measurements of various markers such as C-reactive protein (CRP), procalcitonin (PCT), and interleukin-6 (IL-6)." (PMID 37510189, 2023). "Regarding laboratory results at admission, increased levels of white blood cell (P < .0001), CRP (P < .0001), PCT (P < .0001) and serum creatinine (P < .0001), while decreased levels of blood platelet (P = .0287) and albumin (P = .0003) were observed in sepsis patients compared to HCs." (PMID 36961174, 2023). "For this reason, the diagnosis of culture negative sepsis is often made in neonates with clinical presentations consistent with sepsis and abnormal non-specific laboratory inflammatory indicators such as C-reactive protein (CRP), procalcitonin (PCT), and complete blood cell (CBC) counts." (PMID 37107103, 2023). "Inflammation, infection, and tissue damage may lead to an increase in CRP, and sepsis is not an exception." (PMID 37371588, 2023). "Outside from bacterial meningitis, more than 250 biomarkers have been evaluated over the last few decades, and while C-reactive protein and procalcitonin as host-response biomarkers are frequently used in clinical care, none of them precisely differentiates between sepsis and sepsis-like syndromes." (PMID 37046531, 2023). "However, it is not good in predicting SIRS or sepsis after PCNL compared to PCT, mainly because CRP is more susceptible to rheumatic diseases, malignancies and drug reactions compared to PCT." (PMID 37063849, 2023). "Furthermore, CRP seems to be pivotal for the discrimination between culture-positive and culture-negative sepsis, while YKL-40 did not enable this discrimination in our pilot study sample." (PMID 37238320, 2023). "However, the limitation of IL-6’s short half-life, especially for patients not admitted on the first day of sepsis, can be mitigated through the complementary consideration of CRP levels." (PMID 38255366, 2023).
Sepsis (continued). "Moreover, it was confirmed that the onset of sepsis could be predicted earlier via increased PSP/Reg levels than via conventional inflammatory factors, such as C-reactive protein and procalcitonin." (PMID 37215716, 2023). "In horses, CRP is a moderate APP, as it begins to increase approximately 3–5 days after the inflammatory stimulus, and elevated concentrations have been reported in horses with sepsis, colic, enteritis, and horses that underwent experimental jejunojejunostomies." (PMID 36670767, 2023). "The median CRP levels in the sepsis group (n = 16), pneumonia group (n = 134), and non-infection group (n = 214) were 18.80 mg/L, 6.015 mg/L, and 3.920 mg/L, respectively; the CRP level in the sepsis group was higher than that in the non-infection group (P = 0.009)." (PMID 36877734, 2023). "In the setting of routine NHS care, if this trial finds that a treatment protocol based on monitoring CRP or PCT safely allows a reduction in duration of antibiotic therapy, and is cost effective, then this has the potential to change clinical practice for critically ill patients with sepsis." (PMID 37841304, 2023). "While the introduction of SOFA scores has helped to standardize the clinical management of sepsis, existing sepsis markers, such as CRP, PCT, and IL-6, may not always accurately predict patient outcomes." (PMID 37510189, 2023). "Additional observational studies have reported higher CRP, NLR and LDH values in non-survivors, and their association with an increased risk of developing acute respiratory distress syndrome, cytokine release syndrome and sepsis (reviewed in." (PMID 37388734, 2023). "Finally, omentin-1 at sepsis onset presented a significant positive correlation only with CRP, but not with procalcitonin, IL-1β, IL-6, IL-10, or suPAR." (PMID 37241065, 2023). "In conclusion, if this trial finds that a treatment protocol based on monitoring CRP or PCT safely allows a reduction in duration of antibiotic therapy, and is cost effective, then this has the potential to change clinical practice in terms of how patients with sepsis are managed." (PMID 37841304, 2023). "We conducted a systematic review a systematic review and meta-analysis to determine, in critically ill adults with sepsis, whether procalcitonin (PCT), C-reactive protein (CRP), interleukin-6 (IL-6), and presepsin (sCD14) are independent prognostic factors for mortality." (PMID 37537680, 2023). "The uric acid (3.77±1.6), CRP (17.7±10.6), white blood count (WBC) (14,562.3±5,062.7) and eosinophil (618.5±472.1) values were statistically significantly higher in the proven sepsis group than in the clinical sepsis group (p=0.022; p<0.001; p=0.002; p=0.036, respectively)." (PMID 37398776, 2023). "We hypothesized that assessing DNI and MPC together in patients with suspected sepsis can provide a more robust and accurate diagnosis of sepsis and prognostic prediction than evaluating DNI or MPC alone, as well as other biomarkers, like CRP and procalcitonin." (PMID 38137411, 2023). "Finally, in a recent South Korean prospective observational study among 420 ER patients, presepsin performed better than CRP in terms of differentiating between non-infectious organ failure, sepsis, and septic shock, defined according to Sepsis-3 criteria." (PMID 36941681, 2023). "Moreover, as CRP and PCT production depends on cytokine release, it was thought that the measure of cytokines could offer an earlier and more effective evaluation of sepsis development compared to the traditionally used biomarkers." (PMID 37627653, 2023). "None of our patients had fever at presentation, thus collaborating with the complete blood count result findings which were not suggestive of sepsis, even though a CRP which could not be done may have been a better indicator." (PMID 37518070, 2023).
Sepsis (continued). "In addition, both molecules strongly correlated with SOFA score in sepsis and septic shock patients (PTX3: r=0.44, p<0.0001; sIL-1R2: r=0.35, p<0.0001), confirming data obtained in earlier studies, as well as with PCT, CRP and clinical parameters of severity." (PMID 36189302, 2022). "However, there are no available data regarding the clinical value C-reactive protein-to-albumin ratio (CAR) in identifying sepsis in neonates with pneumonia." (PMID 35873709, 2022). "ROC curve analysis revealed C1INH expression could differentiate between cohorts with/without subsequent development of sepsis, and the discrimination ability was enhanced when combined with circulatory IL-6 and CRP levels (AUC = 0.926, 95%CI = 0.87-0.97)." (PMID 35669402, 2022). "Additionally, we also evaluated the ability of CRP and ALB to predict severe sepsis." (PMID 35873709, 2022). "In addition to clinical evidence, CRP, a non-specific illness response, can aid in the diagnosis of septicemia." (PMID 36553264, 2022). "Many studies have suggested that CREA, CRP, and PCT may help diagnose sepsis in ICU." (PMID 36189371, 2022). "Therefore, this study was conducted to investigate the correlation between PCT, CRP, and NLR and the prognostic value of bloodstream infection in patients with sepsis, in order to provide a basis for early screening of high-risk patients and to guide clinical treatment." (PMID 35345421, 2022). "MiR-451a was positively associated with TNF-α (rs = 0.206, p = 0.026), IL-1β (rs = 0.209, p = 0.023), CRP (rs = 0.328, p < 0.001), and the APACHE II score (rs = 0.272, p = 0.003), while it did not relate to IL-6 (rs = 0.141, p = 0.129) in the patients with sepsis." (PMID 35992658, 2022). "In terms of infection markers in blood, in addition to white blood cell (WBC) count, C-reactive protein (CRP) and procalcitonin levels were per formed in all sepsis patients of case and control group in early hours of ICU admission to clearly determine the presence and severity of sepsis." (PMID 35950155, 2022). "Numerous studies have been conducted to assess the role of C-reactive protein (CRP), White blood cell (WBC), and other biomarkers for diagnosis of neonatal sepsis, but recently, there are some studies that report the important clinical value of antibacterial peptides for the diagnosis of sepsis." (PMID 35664882, 2022). "The premorbid ambulation ability with the albumin level as an indicator of nutritional status and the C-reactive protein level as an inflammatory biomarker can be combined to predict 28-day mortality in elderly patients diagnosed with sepsis and is not inferior to the SOFA score." (PMID 35962331, 2022). "A previous study with the same polytrauma patient cohort at the University Hospital Zurich has shown that CRP is predictive for sepsis even earlier than PCT, 6-8 hours after admission to the trauma hospital However, in many studies, CRP had no predictive ability for sepsis in trauma patients." (PMID 36816532, 2022). "However, a meta-analysis showed CRP had low sensitivity and specificity to indicate an infection and thus it is not recommended in the current sepsis guidelines as a sepsis biomarker." (PMID 35907902, 2022). "Typically, PCT is a more reliable marker of sepsis than CRP, but not all studies support that." (PMID 35907785, 2022). "However, the sensitivity and specificity of the main laboratory indexes for clinical diagnosis of sepsis are not satisfactory, including C-reactive protein (CRP), interleukin-6 (IL-6), and procalcitonin (PCT)." (PMID 36199375, 2022). "Non-specific blood biomarkers that may predict sepsis include procalcitonin, C-reactive protein and sepsin." (PMID 36004363, 2022). "Obtaining serial CRP, rather than a single test, over the first 24–48 hours from onset of symptoms, increases the negative predictive value (e.g identifying infants without sepsis) to 99%." (PMID 36517750, 2022). "In other words, one cannot safely rule-out sepsis based on a “negative” CRP." (PMID 36517750, 2022).
Sepsis (continued). "Infants represent the most insidious patients as they may not express pain, not have significantly high CRP values and develop complications such as sepsis in a higher proportion of cases." (PMID 35626862, 2022). "PCT has higher specificity than lactate or CRP, and can be used to assess severity of sepsis, but levels may also elevate in response to non-infectious causes, and not all studies support widespread use." (PMID 35867213, 2022). "Articles focussing on CRP and PCT in non-surgical causes of sepsis were also not included." (PMID 36475186, 2022). "We acknowledge that, because of its lack of specificity, serum CRP may be influenced by infection and sepsis in an ICU population." (PMID 35618852, 2022). "However, CRP values do not reflect the acuity as they slowly rise and decrease after several days of treatment, for which CRP is not useful in the early course of sepsis." (PMID 36601152, 2022). "C-Reactive Protein has been the subject of many years of study to observe its dynamics in sepsis; however, it is elevated in any inflammatory condition and is not specific for sepsis." (PMID 35950154, 2022). "However, some studies have shown that CRP is not specific for the diagnosis of sepsis; however, its degree of elevation and course is important for interpretation of the disease." (PMID 36713872, 2022). "Some of the research suggests that it is not the CRP’s absolute value, but the decrease in time that might be a good prognostic factor, especially in life-threatening events, such as sepsis." (PMID 36290272, 2022). "Unless there is clear evidence of sepsis or site-specific infection, empirical antibiotic therapy should be discontinued after 36 h if the blood culture is negative, particularly when there are no other markers of infection (e.g. C-reactive protein)." (PMID 35874568, 2022). "Furthermore, we demonstrated that CRP and PCT were associated with 28-day mortality in patients with sepsis, although CRP was not significantly different." (PMID 35337261, 2022). "Furthermore, we investigated the potential value of hepcidin levels compared to HBP levels and the commonly used biomarkers for sepsis i.e. white blood count (WBC), C-reactive protein (CRP), lactate, and procalcitonin as prognostic markers of outcome of disease." (PMID 36050405, 2022). "Early low CRP, however, cannot exclude sepsis and should not delay pre-emptive initiation of antibiotics and early elevated CRP cannot be consistently interpreted as sepsis since conditions such as pre-eclampsia and fetal distress may increase it." (PMID 35622691, 2022). "This study observed the changes of serum albumin (ALB), prealbumin (PAB), hemoglobin (Hb), C-reactive protein (CRP), immunoglobulin (IgG, IgA, and IgM), APACHE II score before and after treatment to evaluate the efficacy of alanyl glutamine in nutritional support therapy for patients with sepsis." (PMID 33725958, 2021). "The poor predictive quality (AUROC) might be seen from a multivariate perspective in the sense of lacking sepsis cases or the multivariate etiology of CRP increase in a polytrauma patient." (PMID 34884171, 2021). "Accumulating evidence have indicated that CRP, a nonspecific marker of inflammation, is markedly associated with the severity and prognosis of excessive inflammatory responses, such as CVD, T2DM, hemorrhagic stroke, and sepsis in COVID-19 pneumonia." (PMID 34447386, 2021). "Taken together, CRP may not be a specific biomarker of sepsis, but its levels have important reference value in conjunction with other tools, such as PCT and some cytokines." (PMID 33654698, 2021). "On the contrary, the CRP values were 22.16 mg/dL (range, 10.01–40.66) and 10.83 mg/dL (range, 1.15–28.12) in the sepsis group and the non-sepsis group, respectively, and the WBC values were 15.56 × 103/uL (range, 0.71–29.64) and 13.92 × 103/uL (range, 7.01–18.84), respectively." (PMID 33420845, 2021).
Sepsis (continued). "Other biomarkers such as CRP, serum creatinine, total leukocyte count, platelet count could also play a role both independently and in conjunction with AEC to predict outcomes and mortality in cirrhotic patients with sepsis and SIRS." (PMID 33585129, 2021). "The Sepsis + ARDS group had a greater respiratory rate, a lower PaO2/FiO2, a greater SOFA score, and higher levels of lactate (LAC), procalcitonin (PCT), C-reactive protein (CRP), interleukin 6 (IL-6), tumor necrosis factor α (TNFα), IL-10, and FGF21 (all P < 0.05)." (PMID 34154595, 2021). "Therefore, CRP/ALB ratio has been recently identified as a valuable predictor of prognosis in patients with various diseases such as tumor and sepsis 10,17,18, whereas its prognostic role remains unclear in AECOPD patients with HF." (PMID 33746575, 2021). "Finally, 22 variables were significantly associated with D-dimer: respiratory rate, systolic pressure, dyspnea, serum K+, neutrophils, globulin, CRP, ferritin, LDH, PCT, SpO2, blood glucose, BUN, total bilirubin, ALT, AST, CK, mortality, ventilation, ARDS, sepsis, and acute cardiac injury." (PMID 34025688, 2021). "On the other hand, the rise of CRP correlates poorly with the course of the disease and interpretation can be affected by other physiological and pathological factors which make its use as a sole sepsis marker is not advised." (PMID 34691286, 2021). "C-reactive protein (CRP) is a widely studied acute-phase protein, triggered by both infection and inflammation leading to its augmentation, and despite high sensitivity, lack of specificity, restricts its application in sepsis diagnosis." (PMID 33413364, 2021). "Second the adjudicators were not blinded to PCT and CRP values ordered as standard of care, which may have contributed to an overestimation of both the prevalence of sepsis and the performance of these biomarkers." (PMID 34193208, 2021). "Blood examination revealed a white blood cell count, neutrophil count, and C-reactive protein (CRP) level of 270/μL, 40/μL, and 17.92 mg/dL, respectively, which were suggestive of the systemic inflammatory response syndrome including febrile neutropenia (FN) and sepsis." (PMID 33941182, 2021). "The PCT-based score performed well in detecting sepsis with the cut-points of 8 points (AUROC 0.80; 95% confidence interval (CI) 0.74–0.85; sensitivity 0.70; specificity 0.76), which was better than PCT alone, C-reactive protein and infection probability score." (PMID 33481913, 2021). "This study aimed to evaluate whether presepsin could be a valuable marker for detecting severe sepsis, and whether it could predict the therapeutic course in patients with UTI compared with markers already used: procalcitonin (PCT) and C-reactive protein (CRP)." (PMID 34641833, 2021). "The emergence of a persistent lipid profile is accompanied by aberrations in cardiac CRP or Lp(a), suggesting that changes in simple composition of lipid profile may not be the only factors accelerating atherosclerosis post-sepsis." (PMID 34869619, 2021). "Also, the CRP concentration in venous blood plasma resulted in no statistical significance (p > 0.05) when compared to two sepsis (EOS and LOS) and control groups of premature infants." (PMID 33521320, 2021). "Finally, patients with a Sepsis or a bacterial infection are characterized by higher neutrophil count, higher monocyte count, higher NLR, higher Lymphocyte to monocyte ratio, higher CRP, higher d‐dimer, higher troponin I, higher procalcitonin." (PMID 33960733, 2021). "Also mean CRP found to be higher in patients with sepsis in comparison to patients with non-sepsis, and a negligible correlation was found between CRP level and SOFA score (r = 0.255, p = 0.05)." (PMID 34324506, 2021). "It is well known that while immunosuppressed patients may not develop the usual symptoms of sepsis, such as fever, elevation of CRP levels will usually be present." (PMID 33804790, 2021).